MELK (maternal embryonic leucine zipper kinase)
Diseases named in the same sentence as MELK in open-access papers (continued):
Sharing a sentence is not in itself a finding about the gene and the disease.
cervical carcinoma (continued). "Immunohistochemistry indicated that the high expression of MELK in cervical cancer tissues was significantly more than that in the paracancerous tissues." (PMID 30334367, 2018). "In collected cancerous and the corresponding paraneoplastic tissues from 28 cervical cancer patients, 66.67% (4/6) of cervical adenocarcinoma patients and 59.09% (13/22) of squamous cell carcinoma patients displayed MELK high expression results." (PMID 30334367, 2018). "MELK high expression was significantly more in cervical cancer than in the normal or any CIN (P < 0.01)." (PMID 30334367, 2018). "MELK is positively involved in cervical cancer cell proliferation, apoptosis, colony formation, and DNA damage repair." (PMID 30334367, 2018). "In order to study the relationship between MELK and cervical cancer progression, differential expression of MELK mRNA in cervical cancer tissues and normal cervical tissues was determined by analyzing the Oncomine microarray gene expression datasets." (PMID 30334367, 2018). "Our findings in cervical cancer validated that the inhibition of MELK affected the cancer cells’ DNA damage repair." (PMID 30334367, 2018). "Several cervical cancer cell lines were treated with MELK knockdown by siRNA and MELK selective inhibitor OTSSP167." (PMID 30334367, 2018). "Immunohistochemistry, Western blot, RT‐qPCR, CCK8, and immunofluorescence techniques were used to detect the expression of MELK in cervical cancer tissues, paracancerous tissues, and cervical cancer cell lines." (PMID 30334367, 2018). "MELK expression in cervical cancer samples was significantly higher than that in paraneoplastic tissues." (PMID 30334367, 2018). "The findings revealed that the average expression level of MELK mRNA in cervical cancer tissues was significantly higher than that in paired adjacent tissues (P < 0.001, n = 25)." (PMID 30334367, 2018). "Considering that MELK is highly expressed in cervical cancer, we would like to test whether MELK is a potential target for cervical cancer therapy." (PMID 34671205, 2021). "We treated cervical cancer cell lines with the short hairpin RNAs (shRNAs) against MELK to observe whether MELK knockdown would block cervical cancer growth." (PMID 34671205, 2021). "It has been reported that seven patients (78%) had a high T-cell response to MELK peptide, which indicated that MELK might be the target of immunotherapy in cervical cancer patients." (PMID 34671205, 2021). "In this study, we show that MELK is important for cervical cancer growth." (PMID 34671205, 2021). "Our results underpin a vital role for MELK, and it may serve as a therapeutic target for cervical cancer." (PMID 34671205, 2021). "In the current study, we aimed to investigate the role of MELK in human cervical cancer cells." (PMID 34671205, 2021). "In conclusion, we demonstrated for the first time that HPV 18 E6/E7 could regulate MELK through transcription factor E2F1 in cervical cancer." (PMID 34671205, 2021). "Altogether, these results suggest that MELK may play a vital role in cancer cell proliferation and indicate a potential therapeutic target for cervical cancer." (PMID 34671205, 2021). "CRKL depletion significantly alters the retention of variable introns of PTK2B and TSC2, and the inclusion of variable exons of MELK, and these tumorigenesis involving genes might then affect development or progression of cervical carcinoma." (PMID 31133010, 2019). "Maternal embryo leucine zipper kinase (MELK) is highly expressed in a variety of malignant tumors and involved in cell cycle regulation, cell proliferation, apoptosis, tumor formation etc However, the biological effects of MELK in cervical cancer are still uninvestigated." (PMID 30334367, 2018). "Highly expressed MELK correlated with the cervical histopathological grading and greatly increased with the cervical histopathological grading, from normal cervix and cervical intraepithelial neoplasia to cervical cancer." (PMID 30334367, 2018).
cervical carcinoma (continued). "In summary, MELK is highly expressed in cervical cancer and correlates with tumor metastasis." (PMID 30334367, 2018). "MELK knockdown could also aggravate the DNA damage of cervical cancer cells possibly by homologous recombination repair pathway." (PMID 30334367, 2018). "Our data showed that the high expression rate of MELK in cervical cancer patients was 56.92%." (PMID 30334367, 2018). "It suggests that MELK may play an important role in the oncogenic formation and progression of cervical cancer." (PMID 30334367, 2018). "This study aimed to explore the expression of MELK in cervical cancer, as well as its effects on the proliferation, apoptosis, DNA damage repair on cervical cancer cell line in vitro and to provide novel ideas for further improving the clinical efficacy of cervical cancer." (PMID 30334367, 2018). "The aim of this study is to investigate the expression of MELK in cervical cancer, as well as the effect on cancer cell proliferation, apoptosis, and DNA damage repair, so as to provide new ideas for further clinical improvement of cervical cancer." (PMID 30334367, 2018). "The results showed that MELK could significantly affect a variety of cervical cancer cell lines proliferation, colony formation ability and promote cell senescence and apoptosis." (PMID 30334367, 2018). "We found that MELK may be related to the translation of M-phase protein, mitochondrial membrane insertion, and apoptosis of cells, which provides a perspective suggestion for the mechanism of action of MELK in cervical cancer cell division." (PMID 34671205, 2021). "Therefore, MELK may be a novel biomarker predicting the poor prognosis of cervical cancer and a promising therapeutic target for the disease." (PMID 30334367, 2018). "Moreover, the abnormal expression of MELK was related to cervical cancer metastasis at early stage." (PMID 30334367, 2018). "Therefore, MELK may be a predicting marker of poor prognosis of cervical cancer and may also be a new therapeutic target for cervical cancer, providing ideas for improving the therapeutic effect of cervical cancer." (PMID 30334367, 2018). "Two important oncogenic markers for cervical cancer were identified in another two studies, namely the centrosomal protein, 55 Kd (CEP55) and maternal embryonic leucine zipper kinase (MELK)." (PMID 38049868, 2023). "To decipher the mechanism of MELK overexpression in cervical cancer, we knocked down the expression of HPV18 E6/E7 in HeLa cell lines using short hairpin RNAs (shRNAs) and analyzed the effect of E6/E7 knockdown on MELK expression." (PMID 34671205, 2021). "First, MELK expression was activated by the HPV E6/E7 via E2F1 and was necessary for cervical cancer growth." (PMID 34671205, 2021). "The knockdown of MELK with siRNA and OTSSP167 had strong inhibition effects on the proliferation, apoptosis, and colony formation of cervical cancer cells." (PMID 30334367, 2018). "The percentage of high expression MELK was, respectively, 8.33% (1/12) in CIN Grade I, 26.67% (4/15) in CIN Grade II, 44.44% (8/18) in CIN Grade III, and 56.92% (37/65) in cervical cancer patients." (PMID 30334367, 2018). "Thus, MELK may affect the biological behavior of cervical cancer." (PMID 30334367, 2018). "MELK expression elevated with progression and severity of cervical diseases from the normal cervix, CINI, CINII, CINIII to cervical cancer." (PMID 30334367, 2018). "MELK expression was progressively increased from normal cervix, CINI, CINII, CINIII to cervical cancer." (PMID 30334367, 2018). "Indeed, knockdown or inhibition of PLK1, CDK1, AURKA, MELK, and NEK2 resulted in reduction or repression of metastatic potential and invasiveness of various cancer types, including mCRPC and cervical cancer." (PMID 34680307, 2021).
cervical carcinoma (continued). "Furthermore, the BMSC-derived exosomes could efficiently carry miR-144-3p or miR-375 into cervical cancer SiHa or C33A cells, playing significant inhibitory functions in the cell proliferation, invasion and migration via targeting CEP55 or MELK, respectively." (PMID 38049868, 2023). "In addition, MELK overexpression showed little difference in cervical cancer tissues, no matter in different cancer stages, or patients' race, weight, and age." (PMID 34671205, 2021).
lung adenocarcinoma (10 papers, 2016 to 2026). A carcinoma that arises from the lung and is characterized by the presence of malignant glandular epithelial cells. "Moreover, MELK has been reported to be associated with the tumorigenesis of lung adenocarcinoma (LUAD) by increasing the migration and invasion of LUAD cells by regulating the EMT signal pathway." (PMID 37340189, 2023). "Other bimodally expressed genes identified in our analyses, such as FOXM1, MELK, RGS20, and OIP5, have been previously reported to associate with clinical outcomes and play functionally significant roles in lung adenocarcinoma." (PMID 40427178, 2025). "We tried to elucidate the possible roles of maternal embryonic leucine pull chain kinase (MELK) in lung adenocarcinoma (LUAD) growth and metastasis." (PMID 38652219, 2024). "MELK is a potential therapeutic target and biomarker for lung adenocarcinoma." (PMID 38382096, 2024). "maternal embryonic leucine zipper kinase (MELK) expression is elevated in lung adenocarcinoma (LUAD) and promotes the malignant progression of LUAD cells by regulating the PLK1-CDC25C-CDK1 signaling pathway to promote proliferation and inhibit apoptosis-mediated cell scorch." (PMID 35958626, 2022).
liver cancer (8 papers, 2017 to 2025). An epithelial or non-epithelial malignant neoplasm that arises from the liver. "We found that the tumor cell death and antitumor effects caused by MELK knockdown combined with liver cancer thermal ablation may be closely related to FABP5 expression." (PMID 39871325, 2025). "In the ICGC liver cancer dataset, higher expression of MELK was associated with poor OS." (PMID 35511171, 2022). "This study provides a new practical approach to clinically target MELK, which will be beneficial in developing clinical treatments for liver cancer." (PMID 39871325, 2025). "MELK knockdown inhibited liver cancer cell proliferation, migration, tumor growth, and lung metastasis." (PMID 39871325, 2025). "A xenograft tumor model was constructed with Hepa1-6 cells to explore the role of MELK in regulating the sensitivity of liver cancer to RFA." (PMID 39871325, 2025). "Our findings showed that MELK is a crucial factor in liver cancer progression and its sensitivity to RFA." (PMID 39871325, 2025). "TAM infiltration into mouse liver cancers was inhibited by RFA treatment or MELK knockdown, with increased M1 macrophages, decreased M2 macrophages in the TAM cluster, and increased CD8+ T cell infiltration." (PMID 39871325, 2025). "High expression of RRM2, MADAL1, MELK, NCAPG and ASPM were associated with poor OS for liver cancer patients." (PMID 35928445, 2022). "Our previous results showed that MELK knockdown in liver cancer cells could enhance RFA-induced antitumor effects." (PMID 39871325, 2025). "Our results also confirmed that MELK is a potential oncogene in liver cancer." (PMID 39871325, 2025). "Therefore, considering the antitumor properties of MELK in liver cancer, this study provides strong evidence to support the powerful antitumor potential of targeting MELK in combination with RFA in liver cancer." (PMID 39871325, 2025). "In addition, MELK expression was found to be abnormally high in liver cancer tissues, which is crucial for early liver cancer recurrence." (PMID 39871325, 2025). "Targeting MELK may be an effective strategy to enhance the sensitivity of liver cancer to RFA and exert antitumor effects by amplifying and prolonging the RFA-induced immune response against tumor progression." (PMID 39871325, 2025). "In addition, tumor-derived MELK expression promotes liver cancer progression by regulating macrophage polarization and CD8+ T cell infiltration." (PMID 39871325, 2025). "The level of MELK expression in tumor tissues of patients with liver cancer varies from individual to individual, and it is still a question worth exploring whether all patients are effective in combination therapy." (PMID 39871325, 2025). "Therefore, miR-21-5p can facilitate the ferroptosis of liver cancer cells by inhibiting the level of MELK, thereby inhibiting the progression of liver cancer." (PMID 37008632, 2023). "However, whether MELK affects RFA-induced tumor inhibition or immune microenvironment changes in liver cancer is unclear, and its specific role and regulatory mechanism remain unclear." (PMID 39871325, 2025). "We also computationally simulated the molecular anchoring diagram of MELK and FABP5 and created an interaction diagram for FABP5 and MELK in the background based on Western blotting in SK-HEP1 and LM3 liver cancer cells." (PMID 39871325, 2025). "MELK is a therapeutic target by regulating RFA efficacy in HCC, and targeting MELK via RGD-LNPs provides new insight into improving RFA efficacy in HCC clinical treatment and combating the malignant progression of liver cancer." (PMID 39871325, 2025). "Downregulation of MELK, MAD2L1, and CCNB1 can also inhibit cell cycle progression of liver cancer." (PMID 32420375, 2020). "Importantly, combining MELK knockdown with RFA could directly kill tumor cells and inhibit liver cancer growth by enhancing RFA-induced apoptosis." (PMID 39871325, 2025).
astrocytoma (7 papers, 2013 to 2022). "In our previous study, we have also demonstrated that MELK knockdown in malignant astrocytoma cell lines caused a reduction in proliferation and anchorage-independent growth in in vitro assays." (PMID 26973435, 2016). "This study aims to identify proteins associated with MELK pathway in astrocytomas." (PMID 26973435, 2016). "MELK is a member of a subfamily that activates serine/threonine protein kinases, and its expression increases with an increasing degree of malignancy in astrocytomas." (PMID 36238156, 2022). "The results presented herein point stahtmin as a downstream target in the MELK pathway that plays a role in malignant progression of astrocytomas." (PMID 26973435, 2016). "We have previously shown a significant correlation between MELK expression and astrocytoma malignant grade, with the highest expression levels in GBM samples." (PMID 26973435, 2016). "The results presented herein point stathmin as a downstream target in the MELK pathway that plays a role in malignant progression of astrocytomas." (PMID 26973435, 2016). "Both MELK and stathmin expressions in astrocytoma were higher in more malignant astrocytomas (respectively), as represented in the semi-quantitative analysis (4 F and 4 L, respectively)." (PMID 26973435, 2016). "In a previous report, our group has demonstrated a stepwise expression level increase of the serine/threonine kinase Maternal Embryonic Leucine Zipper Kinase (MELK) in parallel with the increasing degree of malignancy in astrocytomas." (PMID 26973435, 2016). "However, the downstream signalling pathway of MELK in cancer cells is still not fully understood, and the putative function of MELK in astrocytomas remains unclear." (PMID 26973435, 2016). "MELK and STMN1 expression status was scored according to the median relative expression values (2−ΔCt) of each grade of astrocytoma." (PMID 26973435, 2016). "MELK expression levels were higher in GBM samples (median value = 0.28, SD ± 1.04) compared with lower grades astrocytomas." (PMID 26973435, 2016). "We analyzed MELK and STMN1 expression levels in the series of tissue samples, which included control NN and astrocytoma of all malignant grades." (PMID 26973435, 2016). "Therefore, STMN1 expression was further analyzed simultaneously with MELK gene expression in a series of astrocytomas of different malignant grades and non-neoplastic (NN) brain tissues." (PMID 26973435, 2016).
breast tumors (7 papers, 2014 to 2024). "In contrast, CN gains of MELK are associated with BLBC, showing significant correlation between mRNA expression and CN in breast tumors and cell lines." (PMID 35749404, 2022). "Although upregulation of MELK in breast tumors has been reported in women of European descent, it has not been evaluated in other ethnicities." (PMID 35749404, 2022). "We detected MELK protein both in nuclei and cytoplasm of breast tumors using previously validated anti-MELK antibody, while human protein atlas data showed that MELK protein was mainly detected in cytoplasm, or both in nuclei and cytoplasm of breast tumors." (PMID 35749404, 2022). "Accordingly, the CN gains appear to contribute to an increase in MELK expression, with a significant correlation between mRNA expression and CN in breast tumors and cell lines." (PMID 35749404, 2022). "We first quantified expression of MELK mRNA in breast tumors, the majority of which were from women of African ancestry." (PMID 35749404, 2022). "Given that there are more high-grade tumors in the BBC than the other subtypes, we sought to determine the correlation of MELK with subtypes of breast tumors within the same grade." (PMID 24844244, 2014). "In five independent cohorts with more than 1500 patients in total, we observed a strikingly similar pattern of MELK expression among these different subtypes of breast tumors." (PMID 24844244, 2014). "The obtained results suggest that MELK could serve as a promising target for treating ERα-positive breast tumors with the ERα-positive/PR-positive/HER2-negative phenotype." (PMID 38589728, 2024). "MELK has been considered a prognostic factor to predict breast tumor recurrence." (PMID 37377604, 2023). "Although MELK has been shown to be significantly up-regulated in breast tumors and to be involved in cell cycle regulation and apoptosis, little is known about the genetic and regulatory factors contributing to the altered expression of MELK in BLBC." (PMID 35749404, 2022). "Since MELK is predominantly overexpressed in basal-like breast tumors, we sought to determine whether MELK plays a role in the proliferation of BBC cells." (PMID 24844244, 2014). "This is consistent with the expression pattern of MELK in primary human breast tumors." (PMID 24844244, 2014). "Furthermore, MELK protein expression levels were high in TNBC tumors compared with normal epithelial tissue or luminal and HER2+ breast tumors." (PMID 37377604, 2023). "In addition, 6/7 PC-CIN genes (CEP55, UBE2C, MELK, TPX2, PTTG1, and CDCA3) were also found to be among the top DEGs identified through comparison of high aneuploidy versus low aneuploidy breast tumors in TCGA." (PMID 32380981, 2020). "Together, these data indicate that MELK expression is highly elevated in breast tumors lacking the expression of ER and PR luminal markers." (PMID 24844244, 2014).